MTOR (mechanistic target of rapamycin kinase)
Diseases named in the same sentence as MTOR in open-access papers (continued):
Sharing a sentence is not in itself a finding about the gene and the disease.
tumor (continued). "Additionally, genomic analyses support the role of G-CSF and MDSCs in mTOR-driven immune suppression and tumor progression." (PMID 30213113, 2018). "Then we identified miR-100 as a crucial player to maintain M2 phenotype of TAMs both in vitro and in vivo by targeting mTOR pathway and upregulating the secretion of IL-1ra that could enhance tumor cell stemness." (PMID 30563983, 2018). "Evidence of the further importance of mTOR or its downstream targets has come from studies showing that OSI027, which binds to the catalytic site of mTOR and blocks its kinase function, inhibits tumor growth and down regulates phospo-4eBP1 in xenografts models." (PMID 29907857, 2018). "Our findings demonstrated that the combination of palbociclib with PI3K/mTOR inhibitors enhances the growth inhibitory effects of the single agents, and impairs tumor cell metabolism, suggesting new therapeutic strategies to challenge the aggressive behavior of TNBC." (PMID 29587820, 2018). "Indeed, key information on rapalogs sensitivity can be collected from genetic investigations of tumor patients prior to mTOR-targeted therapies." (PMID 30564554, 2018). "Consequently, the activation of p‐mTOR S2448 is attainable in two different ways dependent on the individual outfit and capacities of the tumor cells to activate these pathways by upstream kinases." (PMID 28675785, 2017). "Given the broad activity and use of paclitaxel and carboplatin in many tumor types, there is potential to explore this triplet therapy in multiple tumors in which mTOR inhibition may be relevant." (PMID 28595616, 2017). "To investigate whether the enzyme inhibitory properties of SHR8443 translate into modulation of the PI3K/mTOR signaling pathway, we assessed the phosphorylation status of downstream substrates in tumor cell lines with different genetic backgrounds." (PMID 29296217, 2017). "In addition, kinase inhibitors of mTOR provide similar effects on tumor vasculature normalization as rapalogs." (PMID 29104248, 2017). "Furthermore, HSF1 has been found to be a downstream effector of the mammalian target of rapamycin (mTOR) pathway in this tumor type." (PMID 28903330, 2017). "In fact, PI3K and mTOR blockade may result in the activation of compensatory pathways of MAPK that could potentially reduce the anti-tumor effects of PI3K/mTOR inhibitors." (PMID 28002802, 2017). "The alteration of mammalian target of rapamycin (mTOR) pathway is prevailing in tumor." (PMID 28460479, 2017). "In addition, it is established that radiation activates the PI3K/AKT pathway and mTOR inhibitors sensitize tumor and endothelial cells to cisplatin and radiotherapy effects." (PMID 28286604, 2017). "High concentrations of lactate and 2-HG exert tumour promoting potential in a cooperative manner with the surveillance of mTOR activity (e.g. 2-HG initiates DNA hypermethylation and lactate fuels the bioenergetic process) which can be present in the studied HT-1080 cells." (PMID 28578659, 2017). "Although no mutations of mTOR itself are known, alterations of mTOR dependent processes have been described in various tumor entities." (PMID 28591197, 2017). "In addition, it was demonstrated that miRNA-625-3p negatively regulates Sox2, which promotes tumor invasion and metastasis by stimulating EMT via regulation of WNT/β-catenin, and tumor growth via AKT/MTOR signaling pathways." (PMID 28863773, 2017). "However, since inhibition of mTOR has effects on nutrient uptake by tumor cells and alters their metabolism, targeting mTOR signaling to regulate MYC protein is a potential approach." (PMID 28362357, 2017). "However, mTOR regulates a wide variety of molecules and so researchers are looking for which ones are responsible for the formation of the tumours." (PMID 28695825, 2017). "mTOR inhibitors delay tumor progression in part by reducing tumor angiogenesis." (PMID 29104248, 2017). "The mTOR pathway is a major signaling cascade regulating tumor cell growth and metabolism." (PMID 29088718, 2017).
tumor (continued). "This very important observation suggests that mTORC1, besides its well-known function as a tumour promoter, also exhibits tumour suppressor features during nutritional limitation, a conclusion with important consequences in terms of targeting mTOR as anticancer-therapy." (PMID 28112156, 2017). "Other mutations of mTOR have further been identified, but their spatial distribution in a tumor has not yet been revealed." (PMID 28280521, 2017). "The PI3K/AKT/mTOR pathway is a crucial mediator of tumor progression." (PMID 28727815, 2017). "This direct tumor stimulating effect of lal−/− MDSCs is also controlled by mTOR." (PMID 28415797, 2017). "However, temsirolimus, a small-molecule inhibitor of mTOR, displays a limited clinical efficacy, since only a subset of patients with high levels of phosphorylated p70s6 kinase in tumor samples were more likely to benefit from treatment." (PMID 29259986, 2017). "Secondly, our results, that stem cell-mediated invasion depends on aberrant induction of drugable targets, such as mTOR, HIF-1α or MMPs, might open a new window of opportunity to minimise the therapy-associated tumour risk." (PMID 28928383, 2017). "Furthermore, regression analysis showed significant correlation between orthotopic tumor weight and p-mTOR/mTOR ratio (r=0.701, p<0.001)." (PMID 29371937, 2017). "Importantly, the phosphatase and tensin homolog (PTEN) tumor suppressor negatively regulates PI3K/AKT/mTOR signaling by dephosphorylating PIP3." (PMID 28872614, 2017). "It has been reported that AKT/mTOR signaling is activated by several tyrosine kinase receptors and exhibit great role in metabolism, proliferation, and protein synthesis in diversified tumor types." (PMID 29228653, 2017). "Thus, everolimus and metformin both inhibit mTOR signaling and, moreover, differentially target tumor cell glucose metabolism." (PMID 28356082, 2017). "The inhibition of mTOR provides a rationale for metformin to suppress tumor growth." (PMID 28271076, 2017). "Moreover, the subsequent mechanism investigation suggested that CAPN2 promoted tumor progression by activating AKT/mTOR signaling, enhancing epithelial mesenchymal transition (EMT) and MMP9 levels." (PMID 29228653, 2017). "Moreover, mounting evidence has indicated AKT and its downstream molecule mTOR are involved into tumor progression by regulating MMPs family and EMT related markers." (PMID 29228653, 2017). "Several reports have demonstrated over-expression of miR-221-3p and miR-222-3p in human HCC, which is associated with inhibition of apoptosis, activation of the TGF-β, Wnt/β-catenin, and mTOR signaling pathways, cell migration, invasion, and the formation of a more aggressive tumor phenotype." (PMID 29179453, 2017). "Similarly, p-mTOR staining in lung AC was stronger at the interface between the tumor and normal tissues." (PMID 28831205, 2017). "Furthermore, hyperactivation of eIF4E as the result of 4EBP1 inhibition is required for mTOR-mediated tumor development." (PMID 28187001, 2017). "The presented data showed that mTOR complex inhibitors – in parallel reduce tumour growth and migration – have significant inhibitory effect on the productions of both glycolytic lactate and mainly from glutamine sourced 2-HG oncometabolites in vitro and in vivo." (PMID 28578659, 2017). "It is considered that inhibition of mTOR pathway leads to an effective block of abnormal signal transduction and prevent the progression of tumor cells.Therefore, the inhibition of this pathway has been regarded as one of the most promising therapeutic strategies for advanced sarcomas." (PMID 29212287, 2017). "Furthermore, we investigated if PI3K/AKT/mTOR signaling is responsible for DEK-mediated acceleration of tumor cell migration, angiogenesis, and EMT." (PMID 29228721, 2017).
tumor (continued). "In squamous cell carcinoma resistant to PI3K inhibitors, dimerization of AXL with EGFR activates the PLCγ/PKC/mTOR pathway to sustain tumor progression [61••], and in mesenchymal ovarian tumors and cell lines, AXL dimerized with MET, EGFR, and HER2, leading to sustained ERK activation [62•]." (PMID 28251492, 2017). "Interestingly, mTOR related gene sets had similar expression levels in STK11ex1-2 and STK11ex3-9, confirming that both types of tumor share the loss of STK11 tumor suppressor activity and subsequent activation of the mTOR pathway." (PMID 26625312, 2017). "In mammals, the phosphoinositide-3-kinase/protein kinase B/mammalian target of rapamycin (PI3K/Akt/mTOR) pathway is emerging as a critical integrator of intracellular signals, and important for apoptosis, malignant transformation, tumor progression, metastasis and radioresistance." (PMID 28592872, 2017). "Given the major roles of PI3K/mTOR and Hsp90 in regulating tumor cell motility, we evaluated in this study whether their inhibitors, PI-103 and NVP-AUY922 (hereafter denoted as AUY922) have potential as anti-migratory agents in GBM." (PMID 28424411, 2017). "Interestingly, Hermann and coworkers have used a combined experimental approach using both tumor-spheres and tumor xenografts to evaluate the anti-tumor activity of a drug combination involving gemcitabine, a Hedgehog and an mTOR inhibitor." (PMID 29156578, 2017). "Hence, future experiments are needed to identify the effects of mTOR inhibitors on tumor endothelial barrier." (PMID 29104248, 2017). "AKT activation through the mTOR-RICTOR complex was reported in various tumor types." (PMID 28042953, 2017). "Moreover, activation of the mTOR pathway in HCC is associated with less differentiated tumors, earlier tumor recurrence, and worse survival outcome." (PMID 29152112, 2017). "Based on our new results we could suggest targeting mTOR activity depending on the metabolic besides molecular genetic phenotype of tumours to increase the success of the future therapies." (PMID 28578659, 2017). "We thus explored the effect of LNT on the PI3K/Akt/mTOR pathway in MCF-7 tumor-bearing nude mice." (PMID 29156828, 2017). "However, in order to sustain tumor growth progression, MTOR needs to be coopted to promote runaway cell proliferation by driving ribosomal protein synthesis and translation." (PMID 28969664, 2017). "EGR1-induced PTEN expression directly inhibits the PI3K/Akt/mTOR pathway in tumor cells." (PMID 27935858, 2017). "mTOR plays an important role in cell physiology and tissue maintenance, and use of its inhibitors like rapamycin leads to up-regulation of the miR-17-92 cluster and down-regulation of tumor suppressors." (PMID 29050357, 2017). "Furthermore, there is now a strong rationale for co-targeting mTOR with IO agents to enhance their anti-tumor activity." (PMID 28822012, 2017). "GABARAPL1 and GABARAPL1 G116A could present a tumor suppressor role through the inhibition of MTOR which has been previously shown to be involved in cell proliferation and tumor progression." (PMID 28915569, 2017). "Thus, both in vitro and in vivo data strongly suggest that NCTD alone and in combination with crizotinib inhibits tumor growth by autophagic cell death secondary to downregulation of c-Met signaling and subsequent inactivation of mTOR." (PMID 29383132, 2017). "In addition, p38 also induces tumor dormancy, resulting in a survival state and a quiescent state related to drug resistance through activation of the p38α-ATF6α-Rheb-mTOR pathway." (PMID 28537893, 2017). "In addition, there is evidence of anti-tumor activity following mTOR blockade after treatment with rapamycin and its analogs in experimental models of HCC." (PMID 28184024, 2017). "Recent study discovered that mTOR inhibitor rapamycin can attenuate influx of tumor infiltrating Treg cells, yet reduction of Treg influx may not be sufficient enough to overcome impaired DC and T cell activation and differentiation." (PMID 28629173, 2017).
tumor (continued). "PBMR1 mutant tumours are associated with increased activity of TFs/(phospho)proteins that have roles in interleukin signalling and MYC, while regulators with increased activity in BAP1 mutant tumours are involved in DNA damage response, apoptosis, insulin signalling and mTOR signalling." (PMID 28139702, 2017). "In a study done by Sishi and colleagues (2013), the authors showed how manipulation of autophagy, through rapamycin-induced inhibition of mTOR, diminished the cardiotoxic effects of Dox on H9c2 myoblasts, as well as a tumour-bearing mouse model of acute Dox-induced cardiotoxicity." (PMID 28937626, 2017). "To correlate DS brain concentration with the modulation of PI3K/mTOR signaling in U87 tumors, we used immunohistochemical analysis to study the signaling alterations in tumor sections derived from mice at similar time points following a single PO dose of DS (6 mg/kg)." (PMID 28423515, 2017). "Although the role of PTEN expression/function in CSC needs to be studied in more detail, here we show that combined MEK/mTOR inhibition exerts synergistic anti-tumor activity in vitro and, most importantly, in vivo, in a proportion of lung and colorectal CSC-derived models." (PMID 28220839, 2017). "The mutation or deletion of LKB1, a serine/threonine master kinase, has been found in NSCLC, which may cause loss of its tumor-suppressor function and promote tumor growth via the LKB1/AMPK/mTOR pathway." (PMID 28208579, 2017). "Hence, we propose that CD164 overexpression increases cell proliferation and chemoresistance via the PI3K/Akt/mTOR pathway, resulting in the conversion of normal human bronchial epithelial cell to tumor-initiating cells." (PMID 28903328, 2017). "The evaluation of p-4E-BP1 expression in tumor tissues may help patient selection for personalized treatment with mTOR inhibitor to improve clinical outcome." (PMID 29290965, 2017). "Akt, a serine/threonine-specific protein kinase, stimulates mTOR, resulting in protein synthesis increasing via its effectors 4EBP1 and S6K, promoting polysome formation and translation of transcription factors modulating tumour cell growth." (PMID 28060760, 2017). "Reduction of cell proliferation was also observed with activation of AKT and mTOR-dependent cell survival pathways, which may also contribute to the tumor chemoprotection." (PMID 28160570, 2017). "We disclosed that CD164 might be an imperative molecule linking tumor-initiating and chemoresistance because it might activate either the downstream signaling of mTOR or ABC transporters." (PMID 28903328, 2017). "Therefore, inhibition of key proteins in this pathway, such as PI3K, AKT and/or mTOR, can be expected to reduce the migration of tumor cells." (PMID 28424411, 2017). "Thus, our results are in line with these reports and support AKT/mTOR activation as an early mediator of post-surgery tumor cell growth and plasticity." (PMID 29156702, 2017). "This energy stress acts as a press disturbance; the effects of which would be greater in the tumor cells than in the normal cells due to their dependency on fermentation energy metabolism, mitogens, anabolic signaling (IGF-1, mTOR, etc.), elevated redox stress, and mutational load." (PMID 28250801, 2017). "We then determined whether tumour accumulation of FiBYL719 nanoparticles translated in PI3K/AKT/mTOR pathway inhibition in HNSCC tumours." (PMID 28194032, 2017). "Another approach might use EGCG in supplement with TKI or mTOR inhibitors to see if the combination particularly sensitizes the tumor cells as compared to TKI or mTOR inhibitor alone." (PMID 29301217, 2017). "Our study identifies a crosstalk between stromal fibroblasts and epithelial cells under starvation that could be exploited therapeutically to target tumours resistant to PI3K/mTOR inhibition." (PMID 28071763, 2017). "In addition, the expression of raptor in tumor and the binding of raptor and p62 to mTOR were notably decreased in the tumors of mice treated with ginkgetin." (PMID 29190983, 2017).
tumor (continued). "Indeed, mTOR participates in the hypoxic tumor response by stabilizing hypoxia-inducible factor 1α and serves as a signaling intermediary in inflammation-mediated angiogenesis." (PMID 29104248, 2017). "The nested mTOR- and Ras-pathways are of critical importance to maintain tumor growth." (PMID 28562352, 2017). "VEGF/HIF-1α/mammalian target of rapamycin (mTOR) signaling pathway could be related to the change of tumor metabolism; thus expression of mTOR might be altered by Bev therapy." (PMID 29262608, 2017). "Moreover, previous studies suggested that FBXW7 suppressed EMT of tumor cells by targeting c-Myc, Notch, mTOR and RhoA signaling pathway." (PMID 28716020, 2017). "Polycystin-1 and the TSC1/TSC2 tumor suppressor complex both act to suppress the activity of mTOR." (PMID 29479522, 2017). "Indeed, mTOR inhibition exerts potent anti-tumor activity in HNSCC experimental systems, and mTOR targeting clinical trials show encouraging results." (PMID 28822012, 2017). "Because of its role as a central modulator of extracellular and intracellular signaling of mediators and growth factors associated with negative tumor behaviors, the mTOR pathway has become an attractive target for a class of targeted anti-tumor agents." (PMID 28642709, 2017). "mTOR inhibits tumor proliferation and growth, induces apoptosis, and reverses drug-resistance." (PMID 29050283, 2017). "Furthermore, 4EBP1 and p70S6K1, which are regulated by growth factor-mediated mTOR signaling, control tumor development and progression through eIF4E-mediated cap-dependent translation of tumor promoting genes, such as survivin, HIF-1α, cyclin D1, and c-Myc." (PMID 28961193, 2017). "This method has the ability to characterize an individual’s tumor genetic signature and may in the future yield molecular prognostic biomarkers and predictive biomarkers of mTOR sensitivity." (PMID 29212165, 2017). "This and our new results suggest that targeting mTOR activity could have a promising potential in different new combination treatments depending on the metabolic phenotype of tumours." (PMID 28578659, 2017). "Furthermore, a combination of PI3K/AKT/mTOR- and Hh inhibitors have been shown to have more potent anti-tumor effects than either monotherapy." (PMID 28789624, 2017). "A well-known master regulator of tumor and immune cell metabolism is mTOR." (PMID 28337200, 2017). "In this study, we found that, similar to genetic depletion of Snail, pharmacological inhibition of HDAC activity significantly repressed Snail activity by inducing 4E-BP1 expression, and co-targeting HDAC and mTOR resulted in a marked suppression of tumor growth." (PMID 29263324, 2017). "We also demonstrated that decreased TIP30 may facilitate lipid metabolism through the AKT/mTOR/SREBP1 signaling pathway to promote tumor growth in HCC." (PMID 28604762, 2017). "In addition, mTOR inhibitors are able to normalize tumor blood vessels, suggesting a potential use as neo-adjuvant therapy prior to chemo- or radiotherapy." (PMID 29104248, 2017). "mTOR activity was assessed in the xenografted tumour tissue." (PMID 29179444, 2017). "Therefore, we suggest that PI3K-Akt-mTOR pathway activation is correlated with the tumour properties of FTC." (PMID 28427206, 2017). "Moreover, ponatinib showed anti-tumor efficacy in an orthotopic xenograft NB mouse model by blocking the activity of PI3K/AKT/mTOR and JAK/STAT3 signaling pathways." (PMID 27564113, 2017). "As a consequence, metformin inhibits mTOR and glycolysis, thereby inhibiting tumor growth." (PMID 27510264, 2016).